KRTAP19-2 (keratin associated protein 19-2)
Description:
In the hair cortex, hair keratin intermediate filaments are embedded in an interfilamentous matrix, consisting of hair keratin-associated proteins (KRTAP), which are essential for the formation of a rigid and resistant hair shaft through their extensive disulfide bond cross-linking with abundant cysteine residues of hair keratins. The matrix proteins include the high-sulfur and high-glycine-tyrosine keratins.
Synonyms: KAP19.2
Tractability: No criterion of Open Targets' tractability assessment is met for any kind of drug.
Gene: Protein-coding gene on chromosome 21 (30,487,043 to 30,487,436, reverse strand). Ensembl gene ENSG00000186965.
Pathways (Reactome):
Developmental Biology: Keratinization
Gene Ontology:
Molecular function: protein binding
Cellular component: cytosol
Genetic constraint (gnomAD): Loss-of-function variants: 3 observed, 1.29 expected, observed/expected ratio (o/e) 2.33. That is too few expected variants to judge how well the gene tolerates losing a copy. Missense variants: 56 observed, 61.53 expected, observed/expected ratio (o/e) 0.91, 90% interval 0.73 to 1.14. Synonymous variants: 30 observed, 24.91 expected, observed/expected ratio (o/e) 1.2, 90% interval 0.9 to 1.63.